AVP (arginine vasopressin)
Description:
Precursor of Arg-vasopressin, an antidiuretic hormone, and neurophysin 2, its carrier protein. [Arg-vasopressin]: Has a direct antidiuretic action on the kidney, it also causes vasoconstriction of the peripheral vessels. Acts by binding to vasopressin receptors (V1bR/AVPR1B, V1aR/AVPR1A, and V2R/AVPR2). [Neurophysin 2]: Carrier protein that binds to and transports Arg-vasopressin from the hypothalamus to the posterior pituitary gland, protecting it from degradation and facilitating its release.
Synonyms: ARVP; VP; ADH; AVP-NPII; AVRP
Tractability: Small molecule: a structure with a bound ligand is known. Antibody: its Gene Ontology location is reachable by antibodies, with high confidence; UniProt places it where antibodies can reach, with medium confidence; UniProt predicts a signal peptide or a membrane-spanning region.
Gene: Protein-coding gene on chromosome 20 (3,082,556 to 3,084,724, reverse strand). Ensembl gene ENSG00000101200.
Subcellular location: Cytoplasmic vesicle, secretory vesicle; Secreted (Arg-vasopressin); Secreted (Neurophysin 2)
Pathways (Reactome):
Signal Transduction: G alpha (q) signalling events; G alpha (s) signalling events; Vasopressin-like receptors
Disease: Defective AVP does not bind AVPR1A,B and causes neurohypophyseal diabetes insipidus (NDI); Defective AVP does not bind AVPR2 and causes neurohypophyseal diabetes insipidus (NDI)
Transport of small molecules: Organic anion transport by SLCO transporters; Vasopressin regulates renal water homeostasis via Aquaporins
Vesicle-mediated transport: Cargo recognition for clathrin-mediated endocytosis; Clathrin-mediated endocytosis
Circadian clock: BMAL1:CLOCK,NPAS2 activates circadian expression
Gene Ontology:
Molecular function: neuropeptide hormone activity; protein binding; protein kinase activity; V1A vasopressin receptor binding; signaling receptor binding; neurohypophyseal hormone activity; V1B vasopressin receptor binding
Biological process: intracellular signal transduction; negative regulation of apoptotic process; positive regulation of gene expression; symbiont entry into host cell; cell-cell signaling; generation of precursor metabolites and energy; maternal aggressive behavior; positive regulation of systemic arterial blood pressure; positive regulation of vasoconstriction; signal transduction; water transport; grooming behavior; intracellular pH reduction; locomotory behavior; maternal behavior; multicellular organismal response to stress; multicellular organismal-level water homeostasis; negative regulation of female receptivity; negative regulation of transmission of nerve impulse; positive regulation of cell growth; positive regulation of cell population proliferation; positive regulation of cytosolic calcium ion concentration; positive regulation of glutamate secretion; positive regulation of prostaglandin biosynthetic process; response to 2,3,7,8-tetrachlorodibenzodioxine; and 9 more
Cellular component: extracellular region; clathrin-coated endocytic vesicle membrane; cytosol; secretory granule; dendrite; neuronal dense core vesicle; transport vesicle
Genetic constraint (gnomAD): Loss-of-function variants: 10 observed, 6.87 expected, observed/expected ratio (o/e) 1.46, 90% interval 0.86 to 1.92. That is too few expected variants to judge how well the gene tolerates losing a copy. Missense variants: 206 observed, 148.79 expected, observed/expected ratio (o/e) 1.38, 90% interval 1.24 to 1.55. Synonymous variants: 106 observed, 77.68 expected, observed/expected ratio (o/e) 1.36, 90% interval 1.16 to 1.6.
Homologues: Orthologues: chimpanzee AVP (98% identical), macaque AVP (96% identical), dog AVP (92% identical), guinea pig AVP (85% identical), mouse Avp (82% identical), rat Avp (80% identical), pig AVP (76% identical), zebrafish oxt (46% identical), tropical clawed frog oxt (46% identical), zebrafish avp (46% identical). Paralogues in human: OXT (54% identical).
Diseases named in the same sentence as AVP in open-access papers:
AVP is named in the same sentence as 451 diseases in open-access papers, as found by Europe PMC text mining. Sharing a sentence is not in itself a finding about the gene and the disease. The quoted sentences say what the papers report.
Hyponatremia (547 papers, 2004 to 2026). An abnormally decreased sodium concentration in the blood. "In the SIADH, release of AVP cannot be effectively reduced by hypoosmolality and hyponatremia, and this is associated with lowering of the osmotic thirst threshold." (PMID 40869169, 2025). "Elderly females are more susceptible to developing hyponatraemia due to oestrogen-i nduced stimulation of AVP secretion." (PMID 40485652, 2025). "Hyponatraemia in heart failure, particularly when mediated by AVP, is associated with worse clinical outcomes, including increased mortality and morbidity." (PMID 41179034, 2025). "Paraneoplastic causes of hyponatraemia, however, classically arises from the ectopic production of arginine vasopressin of the tumour—commonly described as the Syndrome of Inappropriate Antidiuretic Hormone production (SIADH)." (PMID 40142228, 2025). "The most frequent cause of hyponatremia is water retention due to the increase in blood levels of antidiuretic hormone (vasopressin, AVP)." (PMID 40603486, 2025). "Researchers have explored the role of atrial natriuretic peptide in paraneoplastic hyponatremia associated with cancer, particularly its potential involvement beyond the typical role of arginine vasopressin." (PMID 40142228, 2025). "Psychogenic polydipsia and enhanced AVP secretion associated with hyponatremia were reported in patients with schizophrenia." (PMID 40869169, 2025). "In fact, the Japanese diagnostic criteria for SIADH require the plasma AVP concentration to be uninhibited despite hyponatremia or hypotonicity." (PMID 39847311, 2025). "The ectopic production and secretion of arginine vasopressin were proven in small-cell lung cancer-associated hyponatremia." (PMID 40142228, 2025). "While this study offers valuable insights into arginine vasopressin-associated hyponatraemia, the following limitations should be acknowledged." (PMID 39594934, 2024). "Since 100<300<3.3·120, it can be concluded that while some AVP release is present, it is insufficient as a sole cause for the hyponatremia, and EFWI>0must also hold true and be treated." (PMID 38584119, 2024). "Angiotensin II can cause a worsening of hyponatremia in multiple ways: inducing water and sodium retention by numerous renal mechanisms, thirst stimulation, and the release of AVP." (PMID 36675801, 2023). "Hyponatremia is often associated with diabetes insipidus, which refers to insufficient arginine vasopressin (AVP) secretion or defective renal response to AVP, with clinical manifestations of syndromes such hypoosmolality, polydipsia, and polydipsia." (PMID 37968769, 2023). "AVP-mediated dilutional hyponatremia, fluid accumulation, and vasoconstriction are associated with worsening heart failure in adults." (PMID 37508636, 2023). "Hyponatremia is often associated with diabetes insipidus, which refers to insufficient arginine vasopressin (AVP) secretion or defective renal response to AVP, with clinical manifestations of syndromes such as hypoosmolality, polydipsia, and polydipsia." (PMID 37968769, 2023). "This was the origin of the SIADH theory, which suggests that hyponatremia is caused by impaired renal drainage that results from the action of AVP." (PMID 37968769, 2023). "If AVP was continuously secreted, it would cause abnormal water retention and persistent hyponatremia, which would lead to adverse consequences such as heart failure and edema." (PMID 36157210, 2022). "The classical form of the disorder, associated with hyponatremia, is related to a change in the normal plasma osmolality threshold, in which AVP secretion still occurs with sodium plasma levels of 125–130 mm/L and plasma osmolality between 250 and 275 mOsm/kg." (PMID 34468821, 2022). "Abnormal secretion of AVP can cause the syndrome of inappropriate antidiuresis that leads to hyponatremia, which is an electrolyte disorder often observed in the elderly hospitalized and oncologic patients." (PMID 35874817, 2022).
Hyponatremia (continued). "In the context of the Covid-pandemic it has been shown that arginine-vasopressin is increased in patients with fever and dehydration and associated with hyponatremia and inflammatory disorders." (PMID 36434506, 2022). "Many medications are considered to be among the various causes of hyponatremia, because they either stimulate the release of arginine vasopressin (AVP) or potentiate its action in the kidney." (PMID 34955900, 2021). "As reviewed by Moritz and Ayus, the list of conditions associated with hospital-acquired hyponatremia due to excessive secretion of AVP and water retention is quite long and varied." (PMID 34268347, 2021). "The “syndrome of inappropriate secretion of antidiuretic hormone (SIADH)” is the most frequent cause of hyponatremia, and a variety of drugs can stimulate the release of AVP or potentiate its action." (PMID 34955900, 2021). "AVP is known to be an another cause of volume retention, and increased AVP activity causes a decrease in osmolality accompanied by hyponatremia in HFrEF patients." (PMID 34098878, 2021). "Deficiency in AVP secretion is associated with hyponatremia with plasma sodium levels below 135 mmol/L in humans." (PMID 33052234, 2020). "Although the syndrome of inappropriate antidiuretic hormone secretion, driven by ectopic tumor-producing arginine vasopressin, is the most common cause of hyponatremia directly related to malignancies, it affects only 1%–2% of the entire cancer population." (PMID 32340364, 2020). "CY or active form of CY can either stimulate AVP release or enhance its renal effects and cause hyponatremia finally." (PMID 33235058, 2020). "IL-6-stimulated AVP secretion in euvolemic children has been shown to cause hypo-osmolar hyponatremia." (PMID 31670650, 2020). "In fact, an association between Interleukin-6 and arginine vasopressin has been observed, considering interleukin-6 to be the principal stimulator of arginine vasopressin in marathon runners with hyponatremia." (PMID 31455034, 2019). "Hyponatremic patients with advanced CHF often exhibit abnormally elevated AVP plasma levels, and hyponatremia has been associated with reduced survival and increased complications in CHF." (PMID 28620355, 2017). "The underlying diagnosis that placed patients at risk for elevated AVP levels and hyponatremia were primarily respiratory and central nervous system disorders." (PMID 27610358, 2016). "In this condition, risk of developing hyponatremia is increased due also to concomitant liver cirrhosis that stimulates arginine vasopressin (AVP) secretion." (PMID 27167519, 2016). "Intravenous normal saline (0.9 % NaCl, 154 mmol/L Na+) administration runs the risk of further aggravating hyponatremia given that AVP levels are bound to be very elevated in this setting." (PMID 26553121, 2015). "In these circumstances, a defect in tubular diluting functions, caused by the secretion of AVP, is likely to underpin the occurrence of hyponatremia and urine osmolality is typically expected to be superior to plasma osmolality." (PMID 26553121, 2015). "Both AVP-dependent and AVP-independent pathways have been postulated as the possible mechanism underlying hyponatremia in these cases." (PMID 26553121, 2015). "Hyponatremia and impaired urinary dilution can be caused by either a primary or a secondary defect in the regulation of AVP secretion or action." (PMID 24558627, 2013). "Although thyroid and adrenal function were not formally assessed, which is recommended before diagnosing inappropriate AVP release, the response of hyponatraemia to malaria treatment was highly suggestive of a causal relationship." (PMID 22280539, 2012). "In recent years, a number of vasopressin receptor antagonists, which inhibit the effects of AVP and thereby increase free water excretion, have been evaluated in hyponatremic patients with cirrhosis or other causes of hypervolemic hyponatremia." (PMID 22732834, 2012).
Hyponatremia (continued). "Hyponatraemia is primarily a water balance disorder and usually caused by increased secretion of arginine vasopressin (AVP)." (PMID 22280539, 2012). "Because of the vascular action of vasopressin, either vasopressin or desmopressin was used to induce hyponatremia to assess whether the observed changes were characteristic of AVP-associated hyponatremia or hyponatremia alone." (PMID 40603486, 2025). "However, hyponatremia is caused not only by adrenal insufficiency but also by inappropriate secretion of arginine vasopressin (AVP)." (PMID 40657233, 2025). "The use of desmopressin was justified because it avoids the potential confounding vascular effects associated with the administration of AVP or that clinical hyponatremia was generally associated with plasma AVP concentrations below the threshold for significant vasopressor activity." (PMID 40603486, 2025). "Apart from stimulating AVP release, there is evidence to suggest that other mechanisms may cause hyponatremia from ASMs." (PMID 38707045, 2024). "The most common cause of hyponatremia is osmotically inappropriate (hereafter: inappropriate) release of arginine vasopressin (AVP) by the posterior pituitary gland, which results in excessive renal water reabsorption by stimulating translocation of aquaporins." (PMID 38584119, 2024). "This is a relevant aspect of fluid therapy, as patients with undiagnosed reduction in intravascular volume and increased plasma levels of the antidiuretic hormone arginine vasopressin are at increased risk for developing hyponatremia if hypotonic fluids are given." (PMID 38010195, 2023). "The mechanism of anticonvulsant-associated hyponatremia has generally been considered inappropriate hypersecretion of AVP, but an experimental study has indicated a direct effect of carbamazepine on the kidney through V2R stimulation without evidence of the increased release of endogenous AVP." (PMID 36233678, 2022). "Loss of intravascular volume (in hypovolemic hyponatremia) and loss of effective intravascular volume (in hypervolemic hyponatremia) can activate the neurohumoral axis, resulting in increased secretion of AVP, renin, angiotensin II, aldosterone, and catecholamines." (PMID 34558033, 2022). "In theory, patients presenting with hyponatremia during admission caused by SIADH could be of higher risk of developing severe hypernatremia later due to depletion of available AVP." (PMID 34156969, 2021). "Apart from elevated AVP-levels, the amount and speed of fluid intake and concomitant low-solute intake constitute important risk factors in the development of clinically relevant hyponatremias in patients undergoing colonoscopies." (PMID 28173768, 2017). "Patients with ACTH deficiency and hyponatremia have elevated plasma AVP concentrations which may be partially baroregulated due to subtle volume contraction." (PMID 26237593, 2014). "Conventional treatment options for hyponatremia, including water restriction and administration of sodium chloride with or without loop diuretics, do not directly address the underlying water retention induced by excess AVP." (PMID 24558627, 2013). "Hyponatraemia is common in severe imported malaria and dysregulation of AVP release has been hypothesized as an underlying pathophysiological mechanism." (PMID 22221299, 2012). "Interestingly a variant of the syndrome of inappropriate antidiuretic hormone secretion, with a hypersecretion of arginine vasopressin, has also been implicated as a mechanism of exercise-associated hyponatremia." (PMID 21766015, 2011). "This could be an addition to the current diagnostic hyponatremia flowcharts: not only is the presence of AVP release established, its relevance is examined as well, further clarifying the underlying pathophysiological mechanism(s) at play during the occurrence and/or exacerbation of hyponatremia." (PMID 38584119, 2024).
Hyponatremia (continued). "Therefore, the development of therapeutic agents acting on different targets with a different mode of action could be useful for the treatment of disorders linked to excessive AVP secretion such hyponatremia and ADPKD." (PMID 33436646, 2021). "In epileptic patients, AVP disbalance or enhancement of the antidiuretic effect, caused by chronic use of certain anti-epileptic drugs, such as phenytoin, carbamazepine and lamotrigine, may lead to hyponatremia and cerebral edema." (PMID 32062761, 2020). "Additionally, there has been mounting evidence that the key pro-inflammatory cytokine IL-6 may serve as the missing link between states of systemic inflammation, a hallmark of post-operative patients, and the release of AVP and subsequent hyponatremia." (PMID 26553121, 2015). "The pathophysiology of hyponatraemia in heart failure is primarily related to the inappropriate secretion of AVP in response to decreased cardiac output and reduced effective circulating volume." (PMID 41179034, 2025). "Many medications can induce hyponatremia, including arginine vasopressin analogs, anticancer chemotherapeutic agents, psychotropic agents, antipsychotics, antidepressants, anticonvulsants, and thiazide diuretics." (PMID 40886330, 2025). "The reduced rates of hyponatremia seen in the patients with diabetes insipidus can be secondary to a decreased volume overload due to the impaired release or action of AVP." (PMID 40217758, 2025). "Blood tests showed that AVP was elevated despite hyponatremia, adrenocortical hormone levels were relatively preserved, and other pituitary hormone levels were decreased." (PMID 40657233, 2025). "These include dilutional hyponatraemia, which is most commonly contributed to by the renin-angiotensin-aldosterone system, AVP, and other neurohormonal mechanisms and is the main driver, as well as hypovolaemic hyponatraemia mainly due to the use of diuretics." (PMID 41179034, 2025). "The hypotonic fluid reduces plasma osmolality, and to protect against hyponatremia the body inhibits arginine vasopressin (AVP) release resulting in a prompt diuresis." (PMID 39940443, 2025). "Brain water content increased in acute AVP- and dDAVP-induced hyponatremia (respectively to 79.52% ± 0.11, n = 6 and to 79.40% ± 0.09, n = 6 vs. 78.36% ± 0.11 in Sham, n = 6, p < 0.001)." (PMID 40603486, 2025). "In this situation, administering a hypotonic solution for maintenance fluid therapy can exacerbate hyponatremia because AVP impairs free water excretion." (PMID 39585356, 2025). "Levels of occludin mRNA were significantly reduced in acute hyponatremia-induced by both AVP (p < 0.001, n = 8) and dDAVP (p < 0.001, n = 6), vs. Sham group (n = 7)." (PMID 40603486, 2025). "We did not observe any differences in the brain concentration of sodium fluorescein between acute AVP- (p = 0.99, n = 6) or dDAVP-induced hyponatremia (p = 0.99, n = 6) vs. Sham group (n = 6)." (PMID 40603486, 2025). "Both SIADH and cerebral salt-wasting syndrome are characterized by hyponatremia and increased uOsm, but plasma AVP and CoP concentrations are increased with SIADH and decreased with CSWS." (PMID 40160705, 2025). "On the other, its determination does not seem capable of simplifying the differential diagnosis of hyponatremia, where persistent secretion of AVP remains the primary mechanism leading to the reduction of electrolyte-free water clearance." (PMID 40317183, 2025). "Nevertheless, overall, the possibility that hyponatremia in a cancer patient is secondary to SIAD due to ectopic AVP secretion is >30%." (PMID 39125971, 2024). "‘SIADH’, ‘hyponatremia’, ‘arginine vasopressin’, ‘tolvaptan’ and ‘sodium’ had high frequencies, which indicated that the keyword are used and discussed frequently in SIAD research." (PMID 38505746, 2024). "Based on the degree of AVP release, again three hyponatremia scenarios (A–C) can be distinguished, where the commonly used cut‐off value Ou<100 mOsmol/kg is taken as evidence of AVP absence." (PMID 38584119, 2024).